GCG (glucagon)
Diseases named in the same sentence as GCG in open-access papers (continued):
Sharing a sentence is not in itself a finding about the gene and the disease.
Obesity (678 papers, 2007 to 2026). Accumulation of substantial excess body fat. "Survodutide is a novel GCG/GLP-1 receptor (GCGR/GLP-1R) dual agonist in clinical development for people with obesity and people with metabolic dysfunction-associated steatohepatitis (MASH)." (PMID 41638399, 2026). "In GLP-2R-deficient ob/ob mice, elevated glucagon levels, alpha cell mass, and hyperglycemia were observed, along with reduced beta cell mass, indicating a complex role in obesity and glucose regulation." (PMID 41575482, 2026). "A multi-agonist approach is a likely road for the future of anti-obesity drug development involving novel receptors such as glucagon and amylin possibly with even more profound weight loss." (PMID 40149944, 2025). "The recent demonstration of the effectiveness of tirzepatide and retatrutide holds promise for combination therapy targeting GLP-1, GIP, and glucagon to promote weight loss and reduce obesity-related co-morbidities." (PMID 40422864, 2025). "This binding not only modulates insulin and glucagon dynamics but also triggers anti-inflammatory responses that help mitigate chronic low-grade inflammation, a hallmark of obesity-related comorbidities." (PMID 40372699, 2025). "Accordingly, many studies have shown that irisin has a potential role in metabolic diseases, such as diabetes and obesity, which can probably be linked to evidence of the regulation of metabolic peptides such as insulin, glucagon, and leptin." (PMID 38790648, 2024). "As with healthy volunteers, infusion of glucagon in patients with overweight/obesity is associated with an increase in plasma insulin and glucose." (PMID 38579751, 2024). "•Long-term glucagon therapy reverts the loss of beta-cell calcium waves and dysglycaemia associated with diet induced obesity." (PMID 38677509, 2024). "Obesity, chronic inflammation, hypertriglyceridemia, or the activity of antagonistic hormones, including glucagon, cortisol, and thyroxin, seem to be major causative factors in IR development." (PMID 37626790, 2023). "Unimolecular dual and triple agonists targeting glucagon and incretin hormone receptors have been shown to promote bodyweight loss, lower glucose levels, and reduce food intake in animal models of obesity." (PMID 34713962, 2022). "There was a decrease in PF concentrations of signaling molecules associated with obesity, namely glucagon, GLP-1, visfatin, and ghrelin." (PMID 36142272, 2022). "When adjusting for clamp glucose levels, obesity (p = 0.033) and insulin resistance (p = 0.009) were associated with elevated glucagon levels." (PMID 33241460, 2021). "When adjusting for glucose levels in linear mixed models, both obesity and insulin resistance were indeed associated with significantly higher glucagon levels during hypoglycaemia." (PMID 33241460, 2021). "In line with these glucagon actions leading to reduced body weight and fat loss, the possible involvement of this hormone in other metabolic disease related to obesity such as hepatic steatosis deserves further investigation." (PMID 31405212, 2019). "More importantly, MAFB was later found tobe a potent regulator of pancreatic α-cell activity and β cell maturation.For instance, MAFB was shown to regulate cell type-specific glucagon gene expressionand associated with islet cell development and obesity." (PMID 29846411, 2018). "When identifying causes of the high fasting glucagon and insulin levels, circulating free fatty acids (FFAs) have been considered since they are elevated in obesity and such elevation is associated with an increased risk of developing T2DM7." (PMID 28680093, 2017). "Under baseline conditions, obesity is normally associated with elevated plasma glucagon and pancreatic α cell activity." (PMID 25472607, 2014). "A possible link between mmu-miR-342-3p and obesity is the glucagon that is a potential target of this miRNA and is implicated in obesogenesis." (PMID 22496873, 2012).
Obesity (continued). "Furthermore, in T1D, the intra-islet regulation of glucagon secretion by insulin is lost, and the prevalence of obesity, dyslipidemia, depression, and other risk factors for CVD is increased." (PMID 39998445, 2025). "Similarly, the GLORY-1 trial investigated the dual GLP-1/glucagon agonist mazdutide in adults with overweight or obesity, demonstrating significant weight loss and metabolic improvements." (PMID 41301492, 2025). "Similarly, phase III data from mazdutide, a GLP-1/glucagon dual agonist, demonstrated significant total weight loss in a dose-dependent manner in Chinese population with overweight or obesity." (PMID 41465555, 2025). "Only a few glucagon infusion studies have been conducted in patients with metabolic-associated disease, and very few compare the effects of glucagon on metabolism in healthy volunteers with its effects on patients with obesity and/or MASLD." (PMID 38579751, 2024). "Important peptide hormones associated with obesity and diabetes are glucagon and insulin." (PMID 38250713, 2024). "However,single agonist peptides activating GLP-1R to stimulate insulin secretionalso suppress obesity-linked glucagon release." (PMID 37523325, 2023). "Furthermore, leptin receptor-deficient mice, a mouse model of obesity and diabetes, and people with endogenous glucagon deficiency (pancreatectomised individuals) treated with glucagon antisense oligonucleotide have increased hepatic fat." (PMID 37209227, 2023). "Moreover, glucagon stimulates energy expenditure, reduces food intake and enhances weight loss in rodent and human studies, which suggests glucagon agonism would be beneficial in obesity." (PMID 36943057, 2023). "Delayed glucagon suppression was clearly associated with obesity and metabolic syndrome." (PMID 36686477, 2022). "Altogether, these new findings about the roles attributed to α cells and glucagon in islet cell functioning and maintenance have spotted glucagon as a potential peptide to be used in a coordinated treatment of deranged carbohydrate metabolism associated with obesity and T2DM." (PMID 36145148, 2022). "One literature showed that inhibition of intestinal FXR or FXR deficiency could promote glucagon-likepeptide-1 (GLP-1) secretion thus improving obesity-induced glucose intolerance and insulin resistance." (PMID 34992541, 2021). "Similarly, we predicted a GCG deficiency and found (using a keyword search) that it is a biochemical marker of the resistance to obesity during a high-fat diet." (PMID 26694100, 2015). "Interestingly, miR-342-3p was associated with obesity in mice, and the possible link between this miRNA and obesity is glucagon, a potential target for miR-342-3p." (PMID 24279768, 2013). "Similarly, in hormones, leptin (P≤ 0.001), insulin (P≤0.001) and glucagon (P≤0.001), and GH (P=0.003) were associated with obesity." (PMID 20300294, 2008). "Moreover, application of Mendelian randomization techniques might elucidate the (suggestive) causal relationship between obesity, insulin resistance, and altered glucagon and gut hormone secretion." (PMID 38087928, 2024). "Excessive weight, obesity, and weight loss through energy restriction can lead to metabolic changes of glucose and lipid that may ultimate result in changes of glucose, insulin, glucagon, and triglyceride in the blood, most of which are “IMAT contributors”8." (PMID 36437293, 2022). "Although both insulin and glucagon are anorexigenic in infusion studies, the elevated levels of these hormones in obesity have little effect on appetite." (PMID 41043686, 2025). "This disentangling of glucagon's role in lipid metabolism is highly important considering the current development of glucagon‐based drugs to treat obesity and MASLD." (PMID 39985139, 2025). "Glucagon, which should be suppressed in the presence of hyperinsulinemia, is also elevated in insulin-resistant individuals with obesity, contributing to the fasting and postprandial hyperglycemia in these individuals." (PMID 41043686, 2025).
Obesity (continued). "In humans, GCG has shown a strong capacity to induce energy expenditure when combined with a single GLP-1R agonist in individuals living with obesity." (PMID 40892365, 2025). "The development and study of new molecules with dual, triple, or quadruple action targeting GLP-1, GIP, glucagon, and IGF-1 is important to cover as many pathogenic links of obesity with as few adverse effects as possible." (PMID 40649920, 2025). "Dual GLP-1/GCG agonists such as mazdutide and survodutide are currently in phase 3 clinical trials as obesity treatments, with pemvidutide having recently completed phase 2 trials." (PMID 40741227, 2025). "Increased pancreatic α cell mass along with fasting hyperglucagonemia despite preserved glucose-mediated glucagon suppression have been emphasized in obesity." (PMID 40069760, 2025). "The development of obesity and hepatic steatosis is thought to disrupt the liver-α cell axis, leading to resistance toward glucagon's effect on amino acid catabolism." (PMID 40980546, 2025). "Efinopegdutide (JNJ-64565111; HM12525A) is also a unimolecular once weekly GLP-1 and glucagon agonist that has been investigated in people with obesity, T2D and MASLD/MASH." (PMID 38302593, 2025). "We noted a positive correlation between fasting glucagon and the studied obesity indices including WC and BMI." (PMID 40069760, 2025). "Semaglutide, which is approved for managing T2D and obesity, works by enhancing insulin secretion, thereby reducing glucagon release, lowering blood glucose levels, and suppressing appetite, leading to weight loss." (PMID 40283457, 2025). "Additional studies carefully considering obesity and T2D are required to investigate the determinants of circulating glucagon levels." (PMID 39868884, 2025). "This confirms that there is an anabolic state in obesity, a condition that is driven by insulin, a hormone that is secreted in a greater proportion than glucagon even in a fasting state." (PMID 38665134, 2024). "Adults with obesity and T2D are characterized by elevated plasma concentrations of glucagon compared with healthy individuals, suggesting a potential resistance of the pancreatic α-cells to insulin." (PMID 38087928, 2024). "We hope to improve our understanding of the glucagon signaling pathway, obesity, and lipid metabolism." (PMID 39196987, 2024). "In a Phase II study involving retatrutide, a triple agonist of glucose‐dependent insulinotropic polypeptide (GIP), GLP1, and glucagon, patients with obesity experienced a 25% reduction in weight." (PMID 38812572, 2024). "In a study where mice with diet-induced obesity were treated with sleeve gastrectomy or calorie restriction so that they lost the same amount of weight, surrogate markers of glucagon resistance improved only in the mice treated with sleeve gastrectomy." (PMID 38579751, 2024). "In adults with obesity and T2D, fasting hyperglucagonemia and a paradoxical increase as well as failure to suppress glucagon in response to an oral glucose challenge was shown." (PMID 39027470, 2024). "High-dose glucagon infusion (12.5 ng/kg/min or 25 ng/kg/min, giving plasma glucagon levels of around 85 pmol/L) reduces circulating amino acids in patients with obesity and increases urinary nitrogen excretion." (PMID 38579751, 2024). "Other studies have explored the impact of menthol supplementation on glucagon, a hormone involved in glucose metabolism, as a preventative measure against obesity induced by an HFD." (PMID 38732127, 2024). "The insulin-glucagon bipolar axis represented in the form of the insulin:glucagon ratio (IGR) is therefore an interesting variable to study in people with obesity and with different glucose tolerance states." (PMID 38665134, 2024). "In conclusion, fasting and dynamic glucagon levels are elevated in young individuals with overweight or obesity and IFG compared to normoglycemic individuals with normal weight." (PMID 39027470, 2024).
Obesity (continued). "One study showed that liraglutide, a GLP-1 receptor agonist approved for human T2D and obesity, improved glycemic control during hyperglycemia in healthy cats by increasing insulin concentrations and decreasing glucagon concentrations." (PMID 38785817, 2024). "The dysregulated of glucose metabolism in obesity results from by both the inadequate increase in insulin secretion through the numerical incretin effect and insufficient suppression of glucagon secretion." (PMID 38966210, 2024). "GLP-1 has demonstrated its efficacy in treating diabetes and obesity by utilizing multiple mechanisms, including stimulating insulin secretion, inhibiting glucagon secretion, protecting β cells and decreasing food intake." (PMID 38440398, 2024). "In patients with obesity undergoing pancreatic clamp, high-dose glucagon infusion suppressed hepatic VLDL–triglyceride secretion, with a corresponding reduction in plasma VLDL–triglyceride levels." (PMID 38579751, 2024). "Adolescents with obesity and insulin resistance displayed elevated fasting glucagon levels and tAUC0-120 for glucagon, compared to insulin-sensitive individuals with obesity or normal weight." (PMID 39027470, 2024). "In a previous study we found higher fasting glucagon in individuals with obesity compared to controls with normal weight to be significantly associated with higher insulin, free fatty acids, triglycerides and visceral adipose tissue (VAT)." (PMID 39027470, 2024). "Adolescents with obesity display similar elevations in fasting glucagon concentrations compared with controls with NW, associating with hyperinsulinemia, visceral adiposity, high plasma free fatty acids, plasma triglycerides, and IGT." (PMID 38087928, 2024). "Since the male PE offspring showed an increased postnatal weight gain, a subset of metabolic active obesity-related hormones, such as Ghrelin, Glucagon, Insulin, Leptin and PYY, were analyzed." (PMID 37108049, 2023). "In summary, although we were not able to fully revert the altered phenotype, GLP-1, GIP and glucagon did improve the metabolic profile of the VAT of subjects with obesity and prediabetes." (PMID 37233628, 2023). "Glucagon is physiologically suppressed after the oral glucose load; however, an impaired glucagon suppression has been described in adults with obesity." (PMID 37847560, 2023). "It has been proposed that glucagon increases with the onset of obesity and fatty liver as a consequence of hepatic glucagon resistance and with insulin resistance due to the inappropriate regulation of glucagon by fasting and a static glucagon/insulin ratio." (PMID 37764697, 2023). "On the other hand, propionate has been shown to produce insulin resistance and hyperinsulinemia, increases glucagon and fatty acid-binding protein production, activates the sympathetic nervous system, and promotes obesity and metabolic abnormalities." (PMID 36992691, 2023). "Serum from DIO-LFD mice had a similar overall suppression of obesity-driven elevation of adipokines except glucagon and TNF-α." (PMID 37698918, 2023). "GCGR agonism has consequently been identified as a possible therapeutic target for obesity, and a number of studies have investigated the effects of acute glucagon administration on energy intake and energy expenditure in humans." (PMID 36123404, 2022). "The hypothalamus can directly impact on obesity development as it is a tissue that regulates food intake by sensing the circulating levels of glucose and glucagon." (PMID 35326371, 2022). "It would therefore seem prudent that any glucagon-based anti-obesity approach is also capable of reducing glucose levels." (PMID 36123404, 2022). "Glucagon is an attractive target for bodyweight management in individuals with obesity due to its ability to reduce food intake and stimulate energy expenditure, potentially without cardiovascular AEs." (PMID 34713962, 2022).
Obesity (continued). "Several of these metabolic effects make glucagon attractive as an anti-obesity agent, but the applicability, especially in type 2 diabetic subjects, is complicated by the inherent risk of inducing hyperglycemia." (PMID 35245328, 2022). "Basal concentrations and responses to an oral glucose tolerance test of glucagon, GLP-1, GIP, CCK, and gastrin at baseline and after matched ~6% weight loss by a CD or a CRHP diet in individuals with T2D and overweight or obesity." (PMID 36061897, 2022). "In turn, the level of glucagon increases with obesity, and its concentration varies in a wide range depending on the nature of the food consumed." (PMID 36291711, 2022). "Investigation of fasting and postprandial proglucagon derived hormones (e.g. glucagon) in adolescents with obesity along the spectrum of glucose tolerance." (PMID 36686477, 2022). "Multivariate regression analysi with standardized coefficients: predictor of glucagon in a pediatric cohort with overweight/obesity (n = 73) matched for BMI-SDS (R2 = 0.336), correct by Bonferroni-Holm algorithm." (PMID 36133310, 2022). "Univariate analysi for fasting glucagon (pmol/L) in patient with overweight/obesity (n = 104#) matched for BMI-SDS." (PMID 36133310, 2022). "Serum samples measured with the obesity plate also revealed reductions in both leptin and glucagon across the study period." (PMID 35574470, 2022). "In adolescents with obesity, glucagon levels are elevated and the progression to T2DM is related to a further increase as well as an early-phase hyperglucagonemic response to OGTT." (PMID 36686477, 2022). "At pharmacological doses, glucagon increases energy expenditure, leading to interest in utilizing the actions of glucagon for the treatment of obesity [13,]." (PMID 36356832, 2022). "HM15211 (Hanmi Pharmaceuticals) is a triagonist with high GCG activity for obesity treatment and a balanced GLP-1 and GIP activity, to neutralize the hyperglycemic risk of GCG." (PMID 34072172, 2021). "Larger studies are necessary to corroborate our findings and establish definitive glucagon doses and cutoffs, especially in patients with extreme obesity or glucose intolerance." (PMID 32720093, 2021). "Obesity and insulin resistance measurements were positively correlated with less suppression of glucagon and more suppression of the PLF/PHF response." (PMID 33241460, 2021). "Several other peptidomimetics, including multitargeted molecules—dual and triple agonists targeting GLP-1, glucagon and gastric inhibitory polypeptide receptors—are in clinical trials as possible future anti-obesity drugs (Williams, Nawaz, and Evans 2020)." (PMID 34867411, 2021). "Over this main effect, GLP-1 and its agonists can reduce the glucagon secretion, slow the gastric transit and decrease the energy consumption extending the effects on treatment of obesity." (PMID 34195230, 2021). "Xenin, an ancient regulatory peptide known as a regulator of insulin and glucagon secretion (thereby an important therapeutic target in DM and obesity), was also shown to be a factor of PCOS pathogenesis." (PMID 33920227, 2021). "Further analysis revealed that EA treatment can reverse the changes in several KEGG pathways caused by obesity: PPAR signaling pathway, glycolysis/gluconeogenesis, calcium signaling pathway, and glucagon signaling pathway." (PMID 33062027, 2020). "Glucagon increases energy expenditure; consequently, glucagon receptor agonists are in development for the treatment of obesity." (PMID 32232363, 2020). "In conclusion, these findings link delta-cell dysfunction and SST resistance in alpha-cells directly to metabolic disease and demonstrated the importance of SST for the regulation of glucagon secretion in obesity and prediabetes." (PMID 32446876, 2020). "Accumulating evidence from human and animal studies shows that plasma glucagon concentrations are abnormally elevated in individuals with obesity and/or diabetes." (PMID 31541100, 2019).